MIR208B (microRNA 208b)
Synonyms: hsa-mir-208b; MIRN208B; mir-208b
Gene: MicroRNA gene on chromosome 14 (23,417,987 to 23,418,063, reverse strand). Ensembl gene ENSG00000215991.
Gene Ontology:
Biological process: miRNA-mediated post-transcriptional gene silencing
Homologues: Orthologues: chimpanzee ptr-mir-208b (100% identical), macaque mml-mir-208b (100% identical), guinea pig MIR208B (95% identical), mouse Mir208b (95% identical), dog MIR208B (92% identical), pig ssc-mir-208b (92% identical), zebrafish dre-mir-736 (74% identical). Paralogues in human: MIR208A (55% identical).